MIR181B1 (microRNA 181b-1)
Synonyms: hsa-mir-181b-1; MIRN181B1; mir-181b-1
Gene: MicroRNA gene on chromosome 1 (198,858,873 to 198,858,982, reverse strand). Ensembl gene ENSG00000207975.
Homologues: Orthologues: chimpanzee ptr-mir-181b-1 (100% identical), macaque mml-mir-181b-1 (99% identical), rat Mir181b1 (95% identical), pig ssc-mir-181b-1 (72% identical), guinea pig MIR181B1 (71% identical), mouse Mir181b-1 (71% identical). Paralogues in human: MIR181B2 (58% identical), MIR181C (44% identical), MIR181A1 (41% identical), MIR181A2 (41% identical).